MPTX1 (mucosal pentraxin 1 (pseudogene))
Synonyms: MPTX1P
Gene: Unitary pseudogene on chromosome 1 (159,268,623 to 159,277,111, forward strand). Ensembl gene ENSG00000215846.
Diseases named in the same sentence as MPTX1 in open-access papers:
MPTX1 is named in the same sentence as 1 disease in open-access papers, as found by Europe PMC text mining. Sharing a sentence is not in itself a finding about the gene and the disease.
MPTX1 shares sentences with these, for which no sentence is quoted: infection (1 paper).